SPP2 (secreted phosphoprotein 2)
Description:
Could coordinate an aspect of bone turnover.
Synonyms: Spp-24; SPP24
Tractability: Antibody: its Gene Ontology location is reachable by antibodies, with high confidence; UniProt places it where antibodies can reach, with medium confidence; UniProt predicts a signal peptide or a membrane-spanning region. PROTAC: its protein half-life has been measured.
Gene: Protein-coding gene on chromosome 2 (234,050,617 to 234,079,344, forward strand). Ensembl gene ENSG00000072080.
Subcellular location: Secreted
Pathways (Reactome):
Metabolism of proteins: Post-translational protein phosphorylation; Regulation of Insulin-like Growth Factor (IGF) transport and uptake by Insulin-like Growth Factor Binding Proteins (IGFBPs)
Hemostasis: Platelet degranulation
Gene Ontology:
Molecular function: endopeptidase inhibitor activity
Biological process: skeletal system development; bone remodeling; protein-containing complex assembly
Cellular component: extracellular region; endoplasmic reticulum lumen; platelet dense granule lumen; protein-containing complex
Genetic constraint (gnomAD): Loss-of-function variants: 30 observed, 24.49 expected, observed/expected ratio (o/e) 1.22, 90% interval 0.92 to 1.65. The upper end of that interval is the gene's LOEUF score, 1.65, which puts it in group 6 of 6, group 1 being the genes least tolerant of losing a copy. Missense variants: 237 observed, 245.16 expected, observed/expected ratio (o/e) 0.97, 90% interval 0.87 to 1.08. Synonymous variants: 89 observed, 83.35 expected, observed/expected ratio (o/e) 1.07, 90% interval 0.9 to 1.27.
Homologues: Orthologues: chimpanzee SPP2 (98% identical), macaque SPP2 (91% identical), guinea pig SPP2 (69% identical), dog SPP2 (66% identical), mouse Spp2 (66% identical), pig SPP2 (65% identical), rat Spp2 (65% identical), zebrafish spp2 (21% identical).
Diseases named in the same sentence as SPP2 in open-access papers:
SPP2 is named in the same sentence as 35 diseases in open-access papers, as found by Europe PMC text mining. Sharing a sentence is not in itself a finding about the gene and the disease. The quoted sentences say what the papers report.
hepatocellular carcinoma (3 papers, 2019 to 2025). A malignant tumor that arises from hepatocytes. "Previous studies have also reported a consistent and significant decrease in SPP2 expression in tumors, with reduced SPP2 levels in hepatocellular carcinoma (HCC) being associated with advanced clinical and pathological features, indicating a potential tumor-suppressive role for SPP2 in HCC." (PMID 40052788, 2025). "The co-expression profile of SPP2 was identified in 22 hepatocellular carcinoma and 21 normal tissues." (PMID 31849319, 2019). "Previous studies have shown that SPP2 inhibits the growth of tumor cells in prostate cancer, pancreatic cancer and hepatocellular carcinoma and attenuates the growth-enhancing effects of BMP2." (PMID 31849319, 2019). "Also noteworthy are the genes SPP2, which encodes a protein of the cystatin superfamily, and CLEC3B, which encodes a lectin type C member 3 of family 3, which is associated with metastasis and tumor invasion in other cancers, such as hepatocellular carcinoma." (PMID 36982287, 2023). "This indicates that SPP2, LECT2, CPS1, and Ribokinase exert tumor suppressive effects in hepatocellular carcinoma." (PMID 31849319, 2019). "SPP2 was co-expressed with LECT2, CPS1, and Ribokinase in hepatocellular carcinoma." (PMID 31849319, 2019).
liver cancer (3 papers, 2019 to 2025). An epithelial or non-epithelial malignant neoplasm that arises from the liver. "In addition to its association with HCC prognosis, SPP2 is related to colorectal cancer, liver cancer, leukemia and pancreatic cancer." (PMID 38057871, 2023). "RT‐qPCR experiments demonstrated that in mouse liver cancer tissues, the expression levels of Spp2 and Adh4 were significantly lower in tumor tissues compared with adjacent nontumor tissues." (PMID 40018995, 2025). "SPP2 was expressed at lower levels in colorectal cancer, leukemia, liver cancer and pancreatic cancer." (PMID 31849319, 2019). "SPP2 was under-expressed in colorectal cancer, leukemia, liver cancer and pancreatic cancer (p < 0.05)." (PMID 31849319, 2019). "On the contrary, SPP2 was found to be deregulated in colorectal cancer, leukemia, liver cancer, and pancreatic cancer." (PMID 31849319, 2019).
prostate carcinoma (3 papers, 2019 to 2021). A carcinoma that arises from epithelial cells of the prostate gland. "Three genes C1orf114, PRAC and SPP2 were reported to be associated with prostate cancer." (PMID 31640538, 2019). "TRPM8 encodes a receptor‐activated non‐selective cation channel involved in detection of sensations such as coolness that also plays a role in prostate cancer cell migration whereas SPP2 is involved in retinitis pigmentosa in humans and its function is to respond to elevated platelet cytosolic Ca2+." (PMID 34096632, 2021). "For SPP2 gene, an amplification pattern of interest was also observed in prostate cancer." (PMID 31849319, 2019).
Cirrhosis (1 paper, 2025). A chronic disorder of the liver in which liver tissue becomes scarred and is partially replaced by regenerative nodules and fibrotic tissue resulting in loss of liver function. "SPP2 may interact with insulin-like growth factor binding protein 1 (IGFBP1), potentially inhibiting the progression of liver fibrosis and cirrhosis." (PMID 40052788, 2025).
colitis (1 paper, 2024). Inflammation of the colon. "In addition, SPP2 is highly expressed in patients with UC and in mice following DSS-induced colitis." (PMID 38398179, 2024). "Interestingly, mice lacking SPP2 exhibited less DSS-induced weight loss, reduced colitis scores, and decreased proinflammatory cytokine secretion; however, mice lacking SPP1 demonstrated enhanced colitis severity." (PMID 38398179, 2024).
cutaneous melanoma (1 paper, 2019). A primary melanoma arising from atypical melanocytes in the skin. "Also, SPP2 mutation was most predominant in cutaneous melanoma and endometrial cancer." (PMID 31849319, 2019). "In addition, SPP1 and SPP2 mutations mainly occurred in cutaneous melanoma and endometrial cancer." (PMID 31849319, 2019).
cyst (1 paper, 2023). A sac-like closed membranous structure that may be empty or contain fluid or amorphous material. "After cyst removal the expression of SPP2 has been suppressed in 12MPS group." (PMID 36631795, 2023).
Glucose intolerance (1 paper, 2020). Glucose intolerance (GI) can be defined as dysglycemia that comprises both prediabetes and diabetes. "Mice with a deletion of the S1P phosphohydrylolase SPP2 exhibited glucose intolerance due to a defect in the adaptation of pancreatic β cell mass, which supports the idea that the rise of endogenous S1P regulated by SphK2 and SPP2 can promote β cell lipotoxicity." (PMID 32668665, 2020).
lung carcinoma (1 paper, 2019). "The overexpression of SPP2 was linked with reduced survival in those with ovarian cancer, whereas it was linked with improved survival in breast and lung cancer patients (p < 0.05)." (PMID 31849319, 2019). "Breast and lung cancer patients with high SPP2 expression had a better prognosis." (PMID 31849319, 2019).
oral squamous cell carcinoma (1 paper, 2022). "have suggested that SPP2 can serve as a biomarker to predict the prognosis of patients with oral squamous cell carcinoma." (PMID 36248822, 2022).
psoriasis (1 paper, 2016). An autoimmune condition characterized by red, well-delineated plaques with silvery scales that are usually on the extensor surfaces and scalp. "Since many inflammatory stimuli enhance the expression and activity of SPP2, the authors of the study suggest that SPP2 may be involved in inflammatory signaling and probably plays a role in the pathogenesis of psoriasis." (PMID 26786937, 2016).
Sepsis (1 paper, 2025). Sepsis is defined as life-threatening organ dysfunction caused by a dysregulated host response to infection. "SPP2 was first evaluated for its individual ability to protect against lethal sepsis challenge with a ST-3 strain of S. pneumoniae (AR003) in a challenge model under conditions where immunization with PCV13 containing CPS3 is completely protective." (PMID 41459499, 2025).
vascular tumour (1 paper, 2022). "The KPNA2, LPCAT1, KIF2C, and SPP2 genes were statistically correlated with pathological stage, histologic grade, ECOG, vascular tumour cell type, and tumour status." (PMID 35915607, 2022).
tumor (16 papers, 2015 to 2025). "Research has demonstrated that SPP2 can inhibit tumor growth and induce tumor apoptosis by eliminating the pro-tumor functions of bone morphogenetic protein 2 (BMP-2) signaling." (PMID 40052788, 2025). "The results showed that CDCA8 and SPP2 methylation levels were decreased in tumor tissues with worse clinical stages." (PMID 38057871, 2023). "The analysis of TCGA data showed that, CFHR4, DNASE1L3, and SPP2 were significantly higher in adjacent non-tumor tissues, while TAF6 was upregulated in HCC tissues." (PMID 36248822, 2022). "One example of an LEG is SPP2 (secreted phosphoprotein 2), which is exclusively expressed in the corresponding non-tumor tissues of HCC." (PMID 30046116, 2018). "In addition, the presence of circulating tumor cells (CTCs), circulating tumor DNA (ctDNA), and changes in the abundance of some proteins (CXCL10, ASPH, SPP2, ENO2, etc) all predicted the risk of postoperative recurrence 8-12." (PMID 39430252, 2024). "The reported data on SPP2, has shown that dramatically induces apoptosis of tumor cell." (PMID 36631795, 2023). "For example, SPP2 expression significantly decreased with advancing tumor grade." (PMID 30046116, 2018). "However, SPP2 is generally lowly expressed in tumors, suggesting that SPP2 may serve as tumor suppressor gene." (PMID 31849319, 2019). "Interestingly, we observed that the expression levels of SPP2 and ADH4 were significantly lower in tumor samples compared with normal samples in the TCGA database." (PMID 40018995, 2025). "Our findings also revealed significant correlations between KPNA2, LPCAT1, KIF2C, and SPP2 expression and three clinical traits, including ECOG (p < 0.01), vascular tumour cell type (p < 0.05), and tumour status (p < 0.05)." (PMID 35915607, 2022). "SPP2 has been shown to bind to BMP-2 and inhibit tumor growth through the blockage of BMP-2." (PMID 31849319, 2019). "For SPP2, although the expressional difference between paired HCC-A tumor and liver samples were not confirmed to be so significant, its negative correlations with HCC-A stage and grade were obvious." (PMID 30755830, 2019). "The real-time quantitative PCR results showed that CFHR4, SPP2, and DNASE1L3 were expressed higher in non-tumor tissues (Non-Tumor) than in tumor tissues (Tumor), and TAF6 was expressed higher in tumor tissues than in non-tumor tissues." (PMID 36248822, 2022).
cancer (6 papers, 2015 to 2023). A tumor composed of atypical neoplastic, often pleomorphic cells that invade other tissues. "Our results suggest that SPP1 and SPP2 may be effective therapeutic or diagnostic targets in certain cancers." (PMID 31849319, 2019). "Further research is required to confirm these results and verify the value of SPP1 and SPP2 as clinical markers of cancer prognosis." (PMID 31849319, 2019). "To resolve these inconsistencies, we systematically analyzed the available data to determine whether SPP1 and SPP2 are prognostic markers in the context of human cancer." (PMID 31849319, 2019). "Our findings indicate that SPP1 and SPP2 genes might play an important role in cancer progression." (PMID 31849319, 2019).
infection (1 paper, 2016). The state of being infected such as from the introduction of a foreign agent such as serum, vaccine, antigenic substance or organism. "Interestingly, SPP-5 is markedly more closely related to SPP-2 (79% similar) and the other infection-induced SPPs than are either SPP-1 or SPP-12." (PMID 27153332, 2016).
mental illnesses (1 paper, 2024). "Notably, no prior study has reported the association of SPP2 with mental illnesses." (PMID 38758284, 2024).
SPP2 also shares sentences with these, for which no sentence is quoted: colorectal cancer (2 papers); leukemia (2); pancreatic cancer (2); autosomal dominant retinitis pigmentosa (1); breast carcinoma (1); endometrial cancer (1); gastrointestinal disease (1); Hearing impairment (1); inflammatory bowel disease (1); liver fibrosis (1); malaria (1); osteoporosis (1); ovarian carcinoma (1); retinal degeneration (1); retinal diseases (1); retinitis pigmentosa (1); ulcerative colitis (1); vision disorder (1).